GATA2 (GATA binding protein 2)
Diseases named in the same sentence as GATA2 in open-access papers (continued):
Sharing a sentence is not in itself a finding about the gene and the disease.
prostate carcinoma (continued). "Importantly, our study demonstrates that the GATA2 inhibitor K7174 perturbs enzalutamide-liganded AR-mediated transcription activation and markedly enhances the ability of enzalutamide to decrease prostate cancer cell proliferation." (PMID 31501863, 2019). "Importantly, FOXA1 and POU2F1 (also known as OCT1) are also known to cooperate with GATA2 and AR in the expression of androgen-regulated genes and FOXA1 is frequently mutated in advanced prostate cancer patients." (PMID 28038451, 2017). "GATA2 and 3 are pioneer factors for prostate cancer and breast cancer." (PMID 28264478, 2017). "By inspection, we also identified at least 10 additional transcription factors within 500 kb of 9 other GWAS loci, that are also reasonable candidates for contributing to prostate cancer risk: SOX13, ZFP36L2, ATOH8, DLX1 & DLX2 (same locus), GATA2, SKIL, SP8, ASCL2, and DPF1." (PMID 24497837, 2014). "In conclusion, the findings of the present study suggest that the GATA2 gene could represent a prostate cancer metastasis-driving gene, but further experimental proof is needed." (PMID 24448395, 2014). "On the other hand, GATA-2 has more-evident effects on prostate cancer cells." (PMID 24886974, 2014). "A similar correlation was found between elevated GATA2 protein expression and malignant progression of prostate cancer, as shown for clinical prostate cancer samples with (i) increased lymph node involvement, (ii) following neo-adjuvant treatment and (iii) development of castration resistance." (PMID 24448395, 2014). "As such, GATA2 could represent a prostate cancer metastasis-driving gene and a potential target for therapy of metastatic prostate cancer." (PMID 24448395, 2014). "In vitro evidence that GATA2 plays a role in prostate cancer metastasis, and the finding that its elevated expression in clinical metastatic prostate cancer tissues correlates with poor patient prognosis, suggest that the GATA2 gene is a potential prostate cancer metastasis-driving gene." (PMID 24448395, 2014). "That the GATA2 gene may have an important role in prostate cancer metastasis is indicated by the effects of its silencing in prostate cancer LNCaP and C4-2 cell lines." (PMID 24448395, 2014). "GATA-2 plays an important role in activating androgen receptor signaling in prostate cancer." (PMID 23516510, 2013). "Moreover, GATA2 expression is associated with more, rather than less, aggressive prostate cancer, with overexpression increasing metastatic capacity, while GATA3 is associated with less aggressive breast cancer and overexpression prevents metastasis." (PMID 38317241, 2024). "Thus, targeting GATA2 is an attractive therapeutic strategy that might improve the clinical outcome of patients with prostate cancer." (PMID 36980710, 2023). "We further wanted to assess if the degradation of GATA2 also occurred in prostate cancer cells that rely on GATA2 for proper AR transcriptional function, or if GATA2 degradation may be a mechanism of protection from AR activity/differentiation in basal-like prostate epithelial cells." (PMID 35203681, 2022). "In addition to its co-factor function, GATA2 might directly regulate androgen receptor mRNA and protein expression in prostate cancer cells." (PMID 31552182, 2019). "Importantly, the ability of K7174 to sensitize prostate cancer cells to enzalutamide treatment indicates that future studies should consider combining GATA2 inhibitors and enzalutamide to improve the therapeutic efficacy of enzalutamide in the treatment of prostate cancer." (PMID 31501863, 2019). "Importantly, the GATA2 inhibitor K7174 inhibits enzalutamide-induced transcription by decreasing binding of the GATA2/AR/Mediator/Pol II transcriptional complex, contributing to sensitization of prostate cancer cells to enzalutamide treatment." (PMID 31501863, 2019).
prostate carcinoma (continued). "Besides, GATA2 is a pioneer transcription factor for androgen receptor (AR) in prostate cancer, and increased GATA2 and its AR-independent transactivation of IGF2 could mediate taxane resistance through the activation of IGF1/insulin receptor signaling." (PMID 30935420, 2019). "Recently, GATA2 is proved to be required for the survival of RAS pathway mutated non-small cell lung cancer (NSCLC) cells, and it has identified that GATA2 as a regulator of chemotherapy resistance and tumorigenicity in lethal prostate cancer through experimental models and clinical databases." (PMID 28114350, 2017). "Furthermore, GATA2 gene silencing in human prostate cancer LNCaP cells led to a marked reduction in cell migration, tissue invasion, focal adhesion disassembly and to a dramatic change in cell transcriptomes, indicating that GATA2 plays a critical role in prostate cancer metastasis." (PMID 24448395, 2014). "GATA2 is a critical pioneer TF for AR, trans-activated IGF2 to mediate taxane resistance in prostate cancer or promote chemoresistance in gastric cancer via the EGFR signalling pathway." (PMID 38126976, 2023). "Several pioneer transcription factors are recognized as drivers of prostate cancer initiation and progression, including the forkhead box A1 (FOXA1) transcription factor, the homeobox protein HOXB13, and the GATA binding protein 2 (GATA2)." (PMID 36212399, 2022). "In the following review, we will discuss the transcription factors FOXA1, HOXB13, GATA2, ERG, and MYC as they relate to the AR cistrome and its transcriptional output during prostate cancer evolution." (PMID 36212399, 2022). "A GATA transcription factor, GATA-2, was found to be involved in EMT processes in prostate cancer and identified as a prognostic marker in colon, hepatocellular, and prostate cancers." (PMID 33557112, 2021). "GATA2 is also overexpressed in AML and drives prostate cancer pathogenesis, especially in castration-resistant settings." (PMID 32493985, 2020). "GATA2 is the most highly expressed member of the GATA family in prostate tissue and is involved in prostate cancer aggressiveness." (PMID 31501863, 2019). "For prostate cancer cells, GATA2 and OCT1 work in a hierarchical network as GATA2 is recruited with AR, followed by OCT1 binding to its motifs." (PMID 28264478, 2017). "In addition to common essential genes, genes with known relevance to prostate carcinoma pathobiology, including AR, FOXA1, HOXB13, GATA2, SPOP, and AKT, were depleted." (PMID 40956611, 2025). "Although another member of the GATA family, GATA2, regulates AR signaling in prostate cancer cells, proteomic studies have not identified GATA2 as being part of the AR interactome in prostate cancer cell lines or primary tissues." (PMID 38317241, 2024). "In LnCAP prostate cancer cells, FOXA1 and GATA2 independently bind to the ABCC4 gene and recruit chromatin loop-forming factors such as MED1 from distal sites to the cluster two region, allowing androgen receptors to bind and promote transcription upon hormone stimulation." (PMID 39114357, 2024). "The same phenomenon was found in additional benign TA prostate cells, i.e., PrEC, EP156T and RWPE-1 cells, but not in LNCaP or VCaP prostate cancer cell lines, in which GATA2 protein levels did not increase substantially due to MG132 treatment." (PMID 35203681, 2022). "GATA2 also regulates important non-androgen responsive genes (e.g. IGF2) involved in prostate cancer progression." (PMID 31501863, 2019). "Provocatively, it was found that FOXA1 also has the potential to reprogram GATA2 and act as a pioneering effect for both AR and GATA2, suggesting that FOXA1 regulates a transcriptional network that controls AR-mediated gene expression in prostate cancer." (PMID 29888169, 2018).
prostate carcinoma (continued). "During human prostate cancer development, GATA3 mRNA levels are found to be significantly reduced in primary prostate tumors, in contrast to GATA2 whose mRNA levels are unchanged in primary prostate tumors and moderately increased in metastatic prostate tumors." (PMID 27374105, 2016). "For example, recent reports demonstrated that high expression of GATA2 and AIB1/SRC3 is predictive of poor outcome in prostate cancer and modulates the expression of key androgen-regulated genes that have potential roles in the transition of prostate cancer cells to aggressive phenotype." (PMID 23887938, 2013). "WT1 could contribute to GATA2 mediated regulation of target genes in prostate cancer cells, if WT1 also physically interacts with GATA2." (PMID 18631392, 2008). "Therefore, we suspect that the pioneer factor nature of GATA2 for AR observed in prostate cancer cells does not apply to the mesonephric mesenchyme during WD development." (PMID 40196482, 2025). "Furthermore, GATA2-mediated increased chromatin accessibility facilitated the binding of other TFs, including androgen receptor (AR) and SRY-Box Transcription Factor 9 (Sox9), to CREs in prostate cancer cell lines." (PMID 40516868, 2025). "The results showed that the “CHANDRAN Metastasis DN” gene signature (genes downregulated in metastatic vs nonmetastatic prostate carcinoma) was the most enriched gene set across all gene sets depleted in PCa tumors with GATA2 gain/amplification in comparison with those GATA2 diploid tumors." (PMID 37550764, 2023). "Interestingly, previous studies have shown that GATA2 and FOXA1 co-occupy 55% of all hormone-responsive AR binding sites in the LNCaP prostate cancer cell line, suggesting a potential cooperative mechanism between these two pioneer transcription factors in regulating the AR cistrome." (PMID 36212399, 2022). "Interestingly, neither LNCaP nor 22Rv1 prostate cancer cells showed substantially increased levels of endogenous GATA2 protein after treatment with the proteasome inhibitor MG132." (PMID 35203681, 2022). "Indeed, FOXA1 has been hypothesized to be a mediator of hormonal response in breast and prostate cancer, and a hormonal regulatory complex involving FOXA1, GATA2 and AR has been shown to control gene expression in prostate cancer." (PMID 32850701, 2020). "Our results suggest that GATA2 directs enzalutamide-induced transcription by recruiting AR, MED1/MED14, and Pol II to regulatory elements of enzalutamide-responsive genes, revealing a novel role of GATA2 in directing antagonist-mediated transcription in prostate cancer." (PMID 31501863, 2019). "As a potential metastasis-driving gene in prostate cancer, GATA2 was lack of research in GC." (PMID 29921304, 2018).
monocytopenia (48 papers, 2012 to 2025). "From a broader perspective, in certain inherited myeloid disorders with GATA2 deficiency, monocytopenia has been identified as a hallmark finding." (PMID 41011079, 2025). "In contrast, GATA2 deficiency generates isolated monocytopenia, correlating with a broadened window for opportunistic pathogens." (PMID 41141324, 2025). "GATA2 deficiency is also known as MonoMAC syndrome because of the typical features of monocytopenia and disseminated MAC." (PMID 39898691, 2025). "GATA2 is an important myeloid lineage transcription factor, mutations in which have been associated with the autosomal dominant and sporadic monocytopenia and mycobacterial infection (MonoMAC) syndrome." (PMID 40762982, 2025). "Monocytopenia is a hallmark of some rare inherited myeloid disorders with GATA2-deficiency, such as the MonoMAC (monocytopenia and mycobacterium avium complex infections) syndrome and the dendritic cell, monocyte, and lymphocyte deficiency, DCML." (PMID 37509235, 2023). "Somatic GATA-2 mutations occur in sporadic forms of myeloid neoplasms as well and have been shown to be associated with monocytopenia, especially if the C-terminal zinc-finger domain is involved." (PMID 37509235, 2023). "We have found one family with Molluscum lesions, pulmonary diseases and COPA deficiency; one patient with HPV lesions, monocytopenia and GATA2 deficiency and two families with HPV lesions, either EV or common warts, lymphopenia and STK4 deficiency." (PMID 37317175, 2023). "In late childhood and early adulthood, GATA2 deficiency patients commonly develop monocytopenia with mycobacterial disease (MonoMAC)." (PMID 35603181, 2022). "B- cell lymphopenia, as well as monocytopenia, are found in more than 75% of GATA2-deficient patients." (PMID 35603181, 2022). "We describe case of 30-years old women with GATA2 novel mutation who present by primary lymphedema, myelodysplastic changes in bone marrow, monocytopenia and history of several recurrent infections (bacterial, mycobacterial)." (PMID 36119727, 2022). "According to 2019 Update of the IUIS Phenotypical Classification, GATA2 deficiency is classified among congenital defects of phagocyte, underscoring the role of monocytopenia as a key feature." (PMID 35769478, 2022). "Heterozygous mutations in the transcription factor GATA2 result in a wide spectrum of clinical phenotypes, including monocytopenia and Mycobacterium avium complex (MAC) infection (MonoMAC) syndrome." (PMID 34051752, 2021). "Twelve mutations in GATA2 were found to be correlated with the autosomal dominant and sporadic monocytopenia and mycobacterial infection (MonoMAC) syndrome." (PMID 32987825, 2020). "The immunological consequences of a prolonged monocytopenia are unclear, those with germline GATA2 mutations associated with monocytopenia have a higher incidence of opportunistic infections, but these mutations cause additional NK‐ and B‐cell cytopenias." (PMID 31338922, 2019). "At the same time, GATA2 deficiency has been linked to four clinical syndromes: NK cell deficiency, but also monocytopenia and mycobacterial infection syndrome, familial MDS and Emberger syndrome." (PMID 29881389, 2018). "MonoMAC refers to a recently described syndrome of MONOcytopenia and Mycobacterium Avium Complex infections characterized by germline GATA2 mutations 44,46." (PMID 25619630, 2015). "Monocytopenia with susceptibility to atypical mycobacterial infection, such as mycobacteriuma avium complex, was described as ‘monoMAC’ and GATA2 mutation was revealed by a candidate sequencing approach." (PMID 25707267, 2015). "Monocytopenia in HCL is less severe than GATA2 deficiency but also known to confer a risk of mycobacterial infection of 4–9%." (PMID 25707267, 2015). "Profound monocytopenia should prompt a consideration of GATA2 deficiency." (PMID 41322420, 2025).
monocytopenia (continued). "GATA2 deficiency syndrome is caused by heterozygous and loss-of-function mutation in GATA2 and displays severe abnormalities in multiple myeloid and lymphoid lineages, including monocytopenia, neutropenia, and dendritic cell deficiency." (PMID 38803659, 2024). "GATA2 deficiency syndrome, caused by germline mutations in the hematopoietic transcription factor GATA2, stands out because multiple lineages can be affected and patients often present with monocytopenia, B cell deficiency, NK (natural killer) cell deficiency and Dendritic Cell deficiency." (PMID 38033856, 2023). "Patients with STK4 and GATA2 deficiencies, reported in this series, have similar clinical and immunological phenotypes than the previous ones: susceptibility to HPVs, T cells lymphopenia and monocytopenia, respectively." (PMID 37317175, 2023). "Notably, P1 presented with persistent verruca vulgaris and monocytopenia was the diagnostic clue suggestive of GATA2 deficiency." (PMID 35603181, 2022). "This is in keeping with patients who deficient in GATA2 who may show phenotypes of monocytopenia, or abnormal granulopoiesis related to MDS." (PMID 34589480, 2021). "When warts are associated with monocytopenia, a GATA2 deficiency must be suspected." (PMID 33066218, 2020). "Monocytopenia, B, and NK lymphopenia were highly suggestive of GATA2 deficiency." (PMID 28747912, 2017). "The combination of warts with monocytopenia is highly suggestive of a diagnosis of GATA2 mutation." (PMID 25707267, 2015). "Marked monocytopenia combined with B-cell lymphopenia led to a suspicion of GATA-2 deficiency." (PMID 25879889, 2015). "Hence, GATA2 mutations cannot explain the high prevalence of monocytopenia in MDS patients." (PMID 37509235, 2023). "Patients with GATA2 deficiency are at high risk for hematologic malignancies and IEI, and patients with MDS exhibit severe peripheral blood monocytopenia and B cell and NK cell lymphopenia." (PMID 40264496, 2025). "In patients followed at the National Institutes of Health (NIH) Clinical Center, most GATA2 haploinsufficient patients had marked monocytopenia, B lymphocytopenia or NK lymphocytopenia, which developed and worsened over time." (PMID 39267745, 2024). "GATA2 deficiency, caused by heterozygous germline GATA2 variants, is associated with MDS/AML, monocytopenia and mycobacterial infections (MonoMAC), dendritic cell, monocyte, B and natural killer (NK) lymphoid deficiency (DMLC), and/or lymphedema." (PMID 38137719, 2023). "Typical syndromes related to GATA2-haploinsufficiency include primary lymphoedema with myelodysplasia (Emberger syndrome), monocytopenia and mycobacterial infection (MonoMAC) syndrome, and dendritic cell, monocyte, B and NK lymphoid (DCML) deficiency." (PMID 30564229, 2018). "Since GATA-2 haploinsufficiency is characterized by monocytopenia, together with B, NK and DC lymphopenia, discovering a population expanded in GATA-2 patients is remarkable." (PMID 30564229, 2018). "Excluding generalized BMF, GATA2 mutation and hairy cell leukaemia (HCL) are two conditions notable for monocytopenia." (PMID 25707267, 2015). "The persistent profound monocytopenia and B- lymphocytopenia at follow up prompted GATA2 sequencing." (PMID 25879889, 2015). "Chronic monocytopenia should never be neglected as there are few diagnostic possibilities in adults, including myelosuppression, hairy cell leukemia, and GATA2 deficiency." (PMID 41322420, 2025). "The main sign that led to the suspicion of GATA2 deficiency was prolonged monocytopenia and absence of monocyte in peripheral blood and bone marrow along with recurrent infections and alveolar proteinosis." (PMID 41322420, 2025). "The first experiences with GATA2 deficiency were published as monocytopenia with susceptibility to non-tuberculosis mycobacterial infections, other atypical infections, and myelodysplasia." (PMID 41322420, 2025).
monocytopenia (continued). "The critical role that GATA2 plays in GMP formation, myeloid differentiation and maturation easily explains the regulatory mechanisms behind the dendritic cell deficiency, monocytopenia, and neutropenia frequently observed in patients that have been diagnosed with GATA2 deficiency syndromes." (PMID 38033856, 2023). "The combination of these phenomena supported the diagnosis of monocytopenia and mycobacterial infection (MonoMAC) syndrome caused by GATA2 gene mutations, with nontuberculous mycobacterial infection as the main clinical feature." (PMID 35096640, 2021). "Considering the monocytopenia and the infectious profile, composed by pyogenic infections, warts and mycobacteria, WS presents certain similarities with the Mono-MAC syndrome, now identified as the consequence of GATA2 mutations." (PMID 23009155, 2012). "At the same time, the advantage in accuracy is absolutely overwhelming for the genes GATA2, MEFV, and NLRP3, which relate with IMD21 (immunodeficiency 21, monocytopenia and mycobacterial infection syndrome), Familial mediterranean fever, and Familial cold autoinflammatory syndrome, respectively." (PMID 39975544, 2025). "While autosomal dominant inheritance patterns of monocytopenia, early MDS/AML, sensorineural hearing loss, and Emberger syndrome in patients with GATA2 haploinsufficiency have been defined, our study was not designed to comprehensively identify inheritance patterns of rheumatological manifestations." (PMID 32433473, 2020).